KRTAP5-2 (keratin associated protein 5-2)
Description:
In the hair cortex, hair keratin intermediate filaments are embedded in an interfilamentous matrix, consisting of hair keratin-associated protein (KRTAP), which are essential for the formation of a rigid and resistant hair shaft through their extensive disulfide bond cross-linking with abundant cysteine residues of hair keratins. The matrix proteins include the high-sulfur and high-glycine-tyrosine keratins.
Synonyms: KRTAP5-8; KRTAP5.2
Tractability: No criterion of Open Targets' tractability assessment is met for any kind of drug.
Gene: Protein-coding gene on chromosome 11 (1,597,177 to 1,598,294, reverse strand). Ensembl gene ENSG00000205867.
Pathways (Reactome):
Developmental Biology: Keratinization
Gene Ontology:
Molecular function: protein binding
Cellular component: cytosol
Genetic constraint (gnomAD): Loss-of-function variants: 0 observed, 0.13 expected, observed/expected ratio (o/e) 0, 90% interval 0 to 1.89. That is too few expected variants to judge how well the gene tolerates losing a copy. Missense variants: 98 observed, 122.54 expected, observed/expected ratio (o/e) 0.8, 90% interval 0.68 to 0.95. Synonymous variants: 43 observed, 49.22 expected, observed/expected ratio (o/e) 0.87, 90% interval 0.68 to 1.13.
Homologues: Orthologues: mouse Krtap5-1 (62% identical), mouse Krtap5-5 (61% identical), mouse Krtap5-22 (60% identical), mouse Krtap5-4 (58% identical). Paralogues in human: KRTAP5-5 (84% identical), KRTAP5-8 (75% identical), KRTAP5-6 (65% identical), KRTAP4-12 (34% identical), KRTAP4-6 (34% identical), KRTAP4-11 (34% identical), KRTAP10-6 (33% identical), KRTAP10-7 (33% identical), KRTAP4-3 (33% identical), KRTAP10-11 (32% identical), KRTAP4-4 (31% identical), KRTAP4-5 (31% identical), and 35 more.